VIM (vimentin)
Diseases named in the same sentence as VIM in open-access papers (continued):
Sharing a sentence is not in itself a finding about the gene and the disease.
adenomyosis (10 papers, 2017 to 2025). The growth of endometrial tissue inside the muscular wall of the uterine corpus. "The results of western blot showed that the expression of the epithelial marker E-cadherin decreased, and the expression of the mesenchymal markers N-cadherin and Vimentin increased in adenomyosis mice compared with control mice." (PMID 36940085, 2023). "The primary endometrial stromal cells of women with adenomyosis were isolated and identified by vimentin and cytokeratin immunofluorescent staining." (PMID 36967761, 2023). "The EMT process was prominent in ectopic endometrial tissue: Vimentin and N-cadherin levels increased in both adenomyosis and endometrioma, while a decrease in the epithelial marker E-cadherin was found only in adenomyotic tissue (p < 0.05)." (PMID 36499654, 2022). "In conclusion, we demonstrate here that TGFβ1, CTGF, and collagen are expressed in subepithelial stroma region of the endometrium with adenomyosis, in which it is abundant of fibroblasts with positive vimentin staining." (PMID 30695033, 2019). "In order to investigate the increase of Vimentin in endometrial gland epithelial cells of Ems, we used Vimentin and E-cadherin (epithelial cell marker) antibodies to perform the immunofluorescence in ectopic and eutopic endometrial tissue sections of adenomyosis patients." (PMID 35379225, 2022). "Consistently, the expression levels of E-cadherin, N-cadherin, Vimentin, and Twist detected by IHC further indicated that EMT occurred in adenomyosis mice." (PMID 36940085, 2023). "Our immunofluorescence results confirmed that vimentin-positive epithelial cells express TGF-β2 proteins in the mutant mice, which suggests that aberrant activation of β-catenin and TGF-β2 plays an important role in the pathogenesis of adenomyosis." (PMID 33060769, 2020). "In addition, we also found that the expression level of Vimentin in stromal cells of the normal adenomyosis tissue is indistinguishable from that of the epithelial cells." (PMID 35379225, 2022). "Therefore, STAT3, VIM, VEGFA and HSP90B1 that were also annotated in interleukin-4 and interleukin-13 signalling in the present GSEA need to be validated to verify potential downregulation of this pathway in women with adenomyosis." (PMID 32933042, 2020).
clear cell carcinoma (10 papers, 2008 to 2022). "Stable downregulation of CK2β in renal proximal tubular (HK-2) and clear cell adenocarcinoma (786-O) cells triggered changes in E-cadherin, vimentin and Snail1 protein levels indicative of epithelial-to-mesenchymal transition (EMT), and increased HIF-α." (PMID 29464030, 2018). "Advancements in detection methods during the 1990s saw the inclusion of IHC as part of the diagnostic arsenal to exclude renal cell and other types of clear cell carcinomas (e.g. negative staining for vimentin that ruled out RCC)." (PMID 34150416, 2021). "Pathology suggested clear cell carcinoma, and immunohistochemistry revealed the expression of CaIX, CD10, vimentin, and CD8/18." (PMID 35060522, 2022). "Renal-derived clear-cell carcinoma was commonly positive for CD10, PAX8, and Vimentin." (PMID 36727056, 2022). "Diagnosis of clear cell carcinoma was based on certain histological characteristics of the tumour and immunohistochemical analysis (PAS staining, keratins AE1/AE3, EMA, cytokeratin 7, cytokeratin 20, melanosomes, vimentin, Chromogranin, Synaptophysin, S-100, SMA)." (PMID 18442419, 2008). "Immunohistochemically, primary clear cell carcinoma of the gallbladder is strongly positive for CK7 but negative for vimentin, and metastatic RCC of the gallbladder is positive for vimentin but negative for CK7." (PMID 29855393, 2018).
depression (10 papers, 2011 to 2024). "A recent study found that cerebral vimentin-immunoreactive astrocytes showed a widespread reduction in depressive disorder patients who died of suicide, suggesting that dysfunction in astrocytes was associated with suicide and depression, and the results of our study provide new evidence for this." (PMID 36161155, 2022). "However, the subgroup analyses of immunohistochemical biomarkers showed that significant inverse associations were present in women with depression who were WT-1-negative and vimentin-negative." (PMID 36556009, 2022). "In particular, ribosomal protein S19, ribosomal protein S12, ribosomal protein S14, vimentin, and ubiquitin-like modifier activating enzyme 1 mediated the therapeutic effects of EXD on depression and hippocampal damage." (PMID 38915473, 2024). "Strikingly, Clomipramine, a 5-hydroxytryptamine receptor (5-HTR) agonist approved for the treatment of depression, impaired GP73-mediated vimentin polymerization to effectively inhibit metastasis of HCC with high GP73 expression, which provided a new strategy against HCC metastasis." (PMID 37564210, 2023). "Astrocytes IR to vimentin (VIM) display different regional densities than GFAP-IR astrocytes in the healthy brain, and so may be differently altered in depression and suicide." (PMID 33613346, 2021). "The expression levels of astrocyte markers (glial fibrillary acidic protein (GFAP), synemin-α, synemin-β, vimentin, nestin) in isolated gray matter from postmortem ACC and DLPFC were determined to investigate the possible involvement of astrocytes in depression." (PMID 31798416, 2019). "The other YWHAZ abnormalities were the interactions with RNPS1 and LGALS1 in schizophrenia; the interactions with MYCBP2, PRDX1 or TP1l in bipolar disorder; the interactions with RPLP2 and VIM in major depression; and the interactions with RPLP0 in both schizophrenia and major depression." (PMID 22373040, 2011).
glomerulosclerosis (10 papers, 2020 to 2025). A hardening of the kidney glomerulus caused by scarring of the blood vessels. "In addition, vimentin is a marker of the epithelial–mesenchymal transition, which is one of several mechanisms that generate myofibroblasts in the kidney and is associated with podocyte dysfunction leading to glomerulosclerosis." (PMID 40223398, 2025). "In an experimental study, PECs of CD44+/+ in mice produce vimentin and α-SMA, that are accompanied by segmental and global glomerulosclerosis." (PMID 37108355, 2023). "Podocyte‐specific deletion of Btg2 protected against the onset of proteinuria and glomerulosclerosis in ADR‐treated mice along with inhibition of EMT markers such as α‐SMA and vimentin while restoring epithelial marker E‐cadherin." (PMID 37749872, 2023). "Both tubulointerstitial fibrosis and glomerulosclerosis characterize the fibrotic kidney in LN, with a wide spectrum of molecular signatures documented, including hyper-expressed α-SMA, collagen, FSP-1, fibronectin, and vimentin." (PMID 40141260, 2025). "Furthermore, SFN treatment (5/6NX + HA + SFN group) significantly reduced the fibrosis area, glomerular sclerosis index, and fibrotic protein levels (COL1A1, VIM, and ACTA2) compared with those in the 5/6NX + HA group." (PMID 32854194, 2020). "An increase in the desmin, vimentin and α-SMA expressions may contribute to the accumulation of ECM and consequent glomerulosclerosis and tubulointerstitial fibrosis considered the end common pathway to all progressive kidney diseases and which can culminate in ESRD." (PMID 37391399, 2023).
metastasis (10 papers, 2014 to 2024). The spread or migration of cancer cells from one part of the body (where they first appeared) to another. "In Kazakh ESCC, the levels of EMT-associated proteins, such as E-cadherin, N-cadherin, and Vimentin, are significantly correlated with lymph node metastasis and distant metastasis as evidenced by our IHC analyses and others'." (PMID 25464508, 2014). "In addition, lymphatic metastasis was associated with increased expression of N-cad and Vimentin, and reduced levels of E-cad and ZO-1." (PMID 38369484, 2024). "This study highlights the potential of vimentin-FBXL14 complexes as a therapeutic strategy to target EMT-induced metastasis disease, and the targeting vimentin by IGFBP-3 contributing to our understanding of the better means to control cancer metastasis." (PMID 33801272, 2021). "Whereas the expression of Vimentin was significantly up-regulated in ESCCs, and the overexpression of Vimentin was closely related to the depth of invasion, clinical stage, lymph node metastasis and vascular invasion of ESCCs." (PMID 31186031, 2019). "Reduced E-cadherin and increased Vimentin expression, the characteristic changes of EMT, identified in 55.0% and 55.7% of primary ICCs, respectively, were correlated with lymphatic metastasis and poorer overall survival (OS) and disease-free survival (DFS) of ICCs." (PMID 24816558, 2014).
periodontitis (10 papers, 2015 to 2026). An acute or chronic inflammatory process that affects the tissues that surround and support the teeth. "It would be intriguing to study the association between the anti-vimentin antibody found in periodontitis patients and OC-genesis in the context of elevated vimentin in periodontitis lesions." (PMID 37190018, 2023). "Mass spectrometry analysis of human gingival crevicular fluid (GCF) from periodontitis sites shows increased abundance of vimentin peptides compared with healthy sites but these findings have not been confirmed by western blotting." (PMID 40346842, 2025). "Conversely, OLN+VIM+ double‐positive cells were abundant near the alveolar bone region in control mice but were scarcely distributed in the gingiva of periodontitis mice (white arrow)." (PMID 39716898, 2025). "By densitometry, ECV levels estimated by immunoblot were > twofold higher in GCF samples from periodontitis sites than healthy sites (p < 0.01), which is in agreement with earlier data using mass spectrometry analysis of vimentin peptides found in GCF." (PMID 40346842, 2025). "Collectively, these findings indicate a potential role for AnxA2 and vimentin in the amplification of the inflammatory response in periodontitis." (PMID 40346842, 2025). "Induction of periodontitis tend to decrease E-cadherin and increase Vimentin in both WT and CsA-treated WT mice." (PMID 38156070, 2023). "An elevated level of vimentin has been reported in the gingival crevice fluid (GCF) of patients with periodontitis." (PMID 37190018, 2023). "Anti-vimentin mAb locally injected into the ligature-attached site during the induction of periodontitis suppressed alveolar bone resorption compared with a local injection of isotype-matched control mAb." (PMID 37190018, 2023). "In the mouse model induced with periodontitis via a ligature attachment, vimentin-positive mononuclear cells were found in the alveolar bone." (PMID 37190018, 2023). "Combination of CsA and periodontitis exhibited additive suppression of E-cadherin and upregulation of Vimentin in Spock1-Tg mice." (PMID 38156070, 2023). "The combination of CsA and experimental periodontitis resulted in the lowest E-cadherin and the highest Vimentin expression in the gingiva of Spock1-Tg mice among all of the mice groups." (PMID 38156070, 2023). "The production of extracellular vimentin (ECV) by hGFs in response to periodontitis is mediated by an AnxA2‐dependent unconventional secretory pathway that may play a role in the amplification of the inflammatory response." (PMID 40346842, 2025). "Experimental periodontitis could induce small downregulation of E-cadherin and upregulation of Vimentin." (PMID 38156070, 2023). "On the other hand, a local injection of anti-vimentin mAb suppressed periodontal bone resorption in vivo instead of promoting it, suggesting that the neutralization of soluble vimentin may be a promising approach for the treatment of periodontitis." (PMID 37190018, 2023). "We immunoblotted GCF samples from periodontitis sites (P; n = 9) and healthy sites (H; n = 8) for ECV and compared the molecular mass of vimentin with cell lysates prepared from hGFs as a positive control (C)." (PMID 40346842, 2025). "IF staining revealed co-localization of Vimentin, p16, and CD81 in LIP gingiva, indicating the presence of senescent CD81+ fibroblasts in the experimental periodontitis model." (PMID 40801798, 2025). "The level of vimentin and CV in the gingival crevicular fluid (GCF) collected on day 7 significantly increased in the group induced with periodontitis compared with that of the periodontally healthy control group." (PMID 37190018, 2023). "Elevated levels of soluble CV and vimentin-bearing mononuclear cells were found in the bone resorption lesions of periodontitis induced in mice in the absence of an anti-CV antibody." (PMID 37190018, 2023).
periodontitis (continued). "According to the immunohistochemistry of the decalcified alveolar bone isolated from mice euthanized on day 7, vimentin-positive mononuclear cells were detected in the tissue of mice induced with periodontitis, but not in the tissue collected from healthy control mice." (PMID 37190018, 2023). "Combination of CsA and experimental periodontitis seemed to additively downregulate E-cadherin but not in Vimentin, suggesting CsA-mediated downregulation of Vimentin might be stronger than periodontitis-induced upregulation of Vimentin." (PMID 38156070, 2023). "A significantly elevated anti-vimentin antibody, but not the anti-MCV antibody, has been reported in patients with periodontitis compared with periodontally healthy control subjects." (PMID 37190018, 2023).
Wilms tumor (10 papers, 2004 to 2025). An embryonal neoplasm characterized by the presence of epithelial, mesenchymal, and blastema components. "Wilms tumours are often positive for keratin, vimentin, desmin, actin, and WT1, which distinguishes this type of tumour from other malignancies." (PMID 40177273, 2025). "Nephroblastomas are generally positive for keratin, vimentin, desmin, actin, and WT1, allowing this form of tumour to be distinguished from other unusual entities." (PMID 40177273, 2025). "The features favoring the diagnosis of blastemal Wilms tumor are young age and positivity of blastemal elements for vimentin, low molecular weight cytokeratin, epithelial membrane antigen, and WT1." (PMID 22312368, 2012). "Although not necessary for the histopathological diagnosis, the immunoprofile of Wilms' tumor shows that blastemal cells regularly express vimentin and may also show positivity for neuron-specific enolase, desmin, and cytokeratin." (PMID 28845162, 2017). "Wilms tumor can be differentiated from MA in staining as it is positive for WT1 and PAX8 and negative for vimentin and CD57." (PMID 38957819, 2024).
adrenocortical carcinoma (9 papers, 2012 to 2024). "We observed that adrenocortical cancer cells may gain mesenchymal characteristics, associated with the expression of mesenchymal markers (e.g., N-cadherin and vimentin) as part of the process towards the acquisition of a fully transformed phenotype." (PMID 25823656, 2015). "Adrenocortical carcinomas are usually positive for synaptophysin and strongly positive for vimentin." (PMID 22400493, 2012). "One of these components stained positively for calretinin and inhibin, which is indicative of adrenal cortical carcinoma; the other exhibited strong expression of vimentin and desmin, which was concordant with sarcomatous change and confirmed the diagnosis of adrenal cortical carcinosarcoma." (PMID 36292108, 2022). "Furthermore, data from bioinformatical analyses have implicated that ANAX1, CYR61, and VIM are mainly associated with the development of PAAD and GBM, while CEACAM1 and EPHA2 are associated with adrenocortical carcinoma." (PMID 34908921, 2021). "Negative immunostaining for vimentin and Melan-A ruled out an adrenocortical carcinoma." (PMID 37218666, 2024).
cervical adenocarcinoma (9 papers, 2010 to 2025). An adenocarcinoma arising from the cervical epithelium. "Studies have shown that Vimentin and ER expression levels in cervical adenocarcinoma are significantly lower than those in endometrial adenocarcinoma." (PMID 40823095, 2025). "Vimentin is characteristically positive in endometrial adenocarcinoma, although positivity has also been reported in cervical adenocarcinomas." (PMID 20199664, 2010). "The prognostic value of vimentin expression determined in tumor cells by immunohistochemistry before treatment was previously shown using univariate and multivariate analyses of overall and disease-free survival of patients with squamous cell CC and adenocarcinoma of the uterine cervix." (PMID 36834676, 2023). "In a study with human cervical adenocarcinoma HeLa cells, it was reported that RGN knockdown increased migration, invasion and metastisation through the upregulation of N-cadherin and vimentin." (PMID 39682121, 2024). "CEA is a useful marker when used along with ER, vimentin, and p16 to distinguish between primary endometrial (ER+, CEA+, vimentin+, p16-) and endo cervical adenocarcinomas (CEA+, ER-, vimentin-, p16+) in preoperative biopsy samples." (PMID 39118789, 2024). "This immunohistochemical (IHC) profile maybe useful in cases of cervical involvement in order to exclude a synchronous cervical adenocarcinoma, which on IHC is positive for CEA and p16 and is negative for vimentin and ER." (PMID 34574048, 2021).
diabetic nephropathy (9 papers, 2014 to 2025). "Increased expression of desmin and vimentin, both observed in the present study, is associated with damage to podocytes in diabetic nephropathy and several other renal disease models." (PMID 26881253, 2016). "The intermediate filament vimentin is a component of the podocyte cytoskeleton, a marker of podocyte maturation, and its expression is decreased significantly in injured podocytes associated with diabetic nephropathy." (PMID 25329154, 2014). "MC has been also implicated as a modality of podocyte loss, as it has been observed in urinary podocytes from patients with diabetic nephropathy, revealing prominent phosphorylated vimentin, a cellular mitosis marker." (PMID 37847555, 2023). "Immunohistochemical double staining for HNF4A and VIM of human kidney biopsies from pathophysiologically and temporally diverse kidney diseases, such as crescentic nephritis and diabetic nephropathy, displayed extensive increases in VIM expression combined with loss of HNF4A expression." (PMID 39954965, 2025). "Therefore, whether the regulation of FRMD3 on vimentin or focal adhesion could underlie the close association of FRMD3 gene variation and diabetic nephropathy could be worthy of further investigation." (PMID 36631457, 2023). "In biopsies from patients with diabetic nephropathy, we have demonstrated that GREM1 is expressed in areas of tubular-interstitial fibrosis and that it colocalizes with profibrotic markers, including TGF-β, αSMA and vimentin." (PMID 25036148, 2014).